CCR4 (C-C motif chemokine receptor 4)
Diseases named in the same sentence as CCR4 in open-access papers (continued):
Sharing a sentence is not in itself a finding about the gene and the disease.
tumor (continued). "CCR4 was negative in six of the seven DE-GDTCL patients tested: the seventh showed CCR4 positivity both on the MF-like plaques and the non-epidermotropic tumour during PCGDTCL progression (patient #19)." (PMID 34842638, 2021). "Knockdown of CNOT3, a subunit incorporated in the CCR4-NOT complex and responsible for deadenylase activity, was shown to induce tumour development in a sensitized drosophila eye cancer model." (PMID 31572192, 2019). "The CCR4-NOT complex, a major deadenylase in mammals, plays dual roles in the control of tumour development." (PMID 31572192, 2019). "The majority of tumor-infiltrating mast cells expressed CXCR4 but not CCR2, CCR4, CCR5, CCR7, CXCR1, CXCR2 or CXCR7, while, mast cells in peritumoral or non-tumor tissues showed lower CXCR4 expression." (PMID 30808413, 2019). "Although CCR4 expression in HCC has not been reported so far, the presence of CCL22, a CCR4 ligand, in tumor tissues and blood of patients with HCC has previously been reported in some studies." (PMID 28959024, 2017). "Although overexpression of CCR4 failed to influent proliferation of HCC cells in vitro apparently, the prominent acceleration on HCC tumor growth in vivo was remarkable." (PMID 28959024, 2017). "Our data showed a numerical, but not statistically significant decrease, in tumor CXCR3+ CD4+ and CD8+ T lymphocytes, whereas CCR4+ CD4+ and CD8+ T lymphocytes were present at equal frequencies in tumor and in unaffected tissue." (PMID 29020986, 2017). "Modules 1–5 were rich in cytokines (e.g., IL6, IL10), cytokine receptors (e.g., CCR2, CCR4), and immune cell markers (e.g., CD3D, CD3E), indicating that the DEGs primarily regulate the immune microenvironment rather than tumor malignancy traits like proliferation and invasion." (PMID 38594692, 2024). "However, in our CCR4−/− model, PDA6606 tumor cells were not affected directly by the genetic knockout of CCR4 because they were implanted, but a benefit of CCR4 loss on survival in non-tumoral cells was shown." (PMID 37371612, 2023). "Therefore, we concluded that the overexpression of CCR4 and CCR2B selectively changes migratory behavior of NK-92 cells without affecting their ability to lyse tumor cells." (PMID 36834542, 2023). "Targeting CCR4 could be a promising migrastatics strategy to reduce cancer cell motility and metastasis in HNSCC without promoting tumor relapse observed during the interruption of CCL2 inhibition." (PMID 35177591, 2022). "CNOT7 is an important subunit of the eukaryote CCR4-NOT protein complex, and it may participate in the regulation of the transcription of multiple tumor microenvironment related proteins." (PMID 35156522, 2022). "In addition, as we showed in the clinical course of Pt.7 cells, ALA-PDT worked regardless of the presence or absence of CCR4 expression on tumor cells, suggesting PDT can work without cross-resistance to CCR4-antibody treatment as well as to chemotherapy." (PMID 33057055, 2020). "Interestingly, among the five chemoattractant ligands for CCR4, only MCP-1 was increased in tumor tissues compared with adjacent nontumor tissues, while RANTES, MIP-1a, TARC, and MDC were not." (PMID 27177223, 2016). "First, none of the ligands for CCR4 and CCR7 had enhanced expression in tumor environment." (PMID 21935436, 2011).
cancer (140 papers, 2011 to 2025). A tumor composed of atypical neoplastic, often pleomorphic cells that invade other tissues. "CCL22 promotes stemness of cancer cells with CCR4 expression, causing cancer cells migration and EMT, as shown on many types of cancers." (PMID 39513112, 2024). "To decipher the molecular mechanism as to how CCL2 enhances HNSCC cell migration, we have intervened in CCR2 and CCR4, which were reported to be associated with cancer cell progression." (PMID 35177591, 2022). "Despite the number of studies dealing with CCR4 genetic variation and cancer is infrequent, huge array of studies linked CCR4 protein expression with cancer." (PMID 25031489, 2014). "Notably, 74 of these genes overlapped with well-known cancer-associated genes (CAGs), such as CCR4, KLF4, FANCG, and NAB2." (PMID 39267784, 2024). "The association of CCR4 overexpression with diseases is not limited to cancer." (PMID 25031489, 2014). "CCR4 might be implicated in TNF-α-regulated cancer cells metastasis." (PMID 27356745, 2016). "In the context of cancer, the chemokine receptors CCR4 and CXCR4 have been extensively investigated." (PMID 41346591, 2025). "Elevated expression of the chemokine receptor CCR4 in tumors correlates with poor prognosis across multiple cancer types and has been extensively studied in ccRCC." (PMID 41301871, 2025). "CCL3 is a monokine with chemokinetic and inflammatorycharacteristics that binds to the CCR4 and CCR5 receptors; it is oneof the main substances produced by CD8+ T cells that suppress virusesthat drive mutation in cancer." (PMID 40047620, 2025). "In vitro experiments showed that employing an anti-CCR4 antibody effectively decreased Treg cell counts, facilitating the activation of cancer/testis antigen-specific T cell responses." (PMID 38928238, 2024). "Immunohistochemical staining of the macrophage marker F4/80 suggested decreased macrophage numbers in the cancer tissue of CCR4−/−." (PMID 37371612, 2023). "Since eTreg-mediated immune evasion mechanisms appear to be crucial in the development of several types of malignancies, CCR4 is a desirable target for cancer immunotherapy." (PMID 37259456, 2023). "We also show that TGF-α promotes the secretion of CCL2 from DRG neurons, which, in turn, activates the cancer cell cytoskeleton through CCR4, paxillin phosphorylation, and cell protrusion formation." (PMID 37607005, 2023). "On the other hand, once fully transformed, invasive cancer cells seem to upregulate TGF-α, which augments NI over induction of CCL2 secretion from neurons, which acts upon CCR4 on cancer cells." (PMID 37607005, 2023). "Further research is undoubtedly necessary to evaluate the role of the CCL2/CCR4 axis in other cancers." (PMID 36555280, 2022). "Therapy with mogamulizumab, a monoclonal-antibody anti-CCR4, promotes a reduction in cancer-cell populations, followed by a decrease in IL-31 levels and itching." (PMID 35742951, 2022). "We also found that TSLP from cancers prepares the metastasis “soil”, such as inducing expression of CCL17 in the lungs to recruit CCR4+ cancer cells and their protector CCR4+FoxP3+ Tregs and Th2-skewed CD4+ T cells." (PMID 36104343, 2022). "In some solid tumors, an increasing number of studies have shown that CCL2, CCL17, and CCL22 with CCR4 expression induced cancer cells migration, EMT, and metastasis in some solid tumors." (PMID 35177591, 2022). "Chemokines (CCR1, CCR2, CCR3, CCR4, CCR5, CCR6, CCR7, and CCR8) and receptor genes (CXCL1-17, CCL1-14, CCL16-26) were positively associated with necroptosis levels in various cancers." (PMID 36170029, 2022). "C–C chemokine receptor 4 (CCR4) has been reported to be predominantly expressed on the cell surface of effector-type Tregs, in both cancer tissues and peripheral blood from patients." (PMID 35449092, 2022). "It has been shown that CCR4 antagonism enhances anti-cancer efficiency of sorafenib and overcomes sorafenib resistance via targeting CCR4+TIL-Tregs." (PMID 36071839, 2022).
cancer (continued). "In this context, several CCR4-targeted cancer immunotherapies have been performed in both animal and human studies, aiming at inhibiting Treg cell-mediated immune suppression." (PMID 34885241, 2021). "This was ameliorated through the addition of a pharmacological inhibitor of CCR4, substantiating CCR4 as a potential means of targeting Tregs for cancer therapy." (PMID 34141625, 2021). "The main focus of this review is CCR4; its expression on normal and malignant T cells and its significance as a therapeutic target in cancer immunotherapy." (PMID 34771703, 2021). "These include anti-CCR4 CAR-T cells, which have proven to be effective against several T-cell malignancies and small-molecule CCR4 antagonists capable of improving the efficacy of anti-cancer vaccines by preventing Treg induction." (PMID 34575965, 2021). "CCR4-inhibition has also been suggested as a means of depleting Tregs for cancer immunotherapy, augmenting cytotoxic T-cell responses." (PMID 34141625, 2021). "Given that chemokines and their receptors are involved in several aspects of cancer biology, CCR4 blockade with monoclonal antibody (mogamulizumab) and inhibitor of chemokine receptor CXCR4 (AMD3100) are being tested in clinical studies." (PMID 32422889, 2020). "These promising in vivo reports are the basis for a clinical trial of anti-CCR4 therapy in renal and other CCR4-overexpressing cancers." (PMID 32422889, 2020). "CCR4 has molecular implications in angiogenesis, and its inhibition has shown anti-cancer properties." (PMID 31484560, 2019). "We believe that the CCR4 immunotoxin will be one of the promising Treg‐targeted immunotherapy drug candidate for combined cancer treatment." (PMID 29873181, 2018). "A monoclonal antibody targeting CCR4 has shown promising results, effectively depleting Treg cells, both in vitro and in clinical trials in human cancer patients." (PMID 29463952, 2017). "Cancer cell-produced CCL22 or CCL17 attracts CC chemokine receptor 4-positive (CCR4+) Treg cells in the TME, which seems to be the most prevalent mechanism for Treg cell migration to tumors." (PMID 29463952, 2017). "Several recent clinical trials have shown that depletion of CCR4-expressing FoxP3+CD4+ Treg cells by anti-human CCR4 monoclonal antibody is a promising approach to augment antitumor immune responses in cancer patients." (PMID 27177223, 2016). "We further demonstrated that matrix metalloproteinase 13 (MMP13) played an important role in CCR4-mediated cancer cell invasion, which is up-regulated by ERK/NF-κB signaling." (PMID 27356745, 2016). "Our hypothesis is that the combined use of a CCR4 antagonist with antibiotic therapy may increase the survival rate after an initial insult and also guarantee long-term survival without immunosuppression, decreasing susceptibility to pulmonary infections, cancers, and cardiovascular diseases." (PMID 26197455, 2015). "CCL22 and CCR4 also play an important role in cancer growth and metastasis, thus many CCR4 receptor antagonists as well as an anti-CCR4 antibody are being developed in the pharmaceutical industry." (PMID 25245466, 2014). "The expression of chemokine receptors is known to be associated with cancer metastases, such as CXCR4, CCR7 and CCR10 in breast cancer and CXCR5, CCR6, CCR7, and CCR4 in pancreatic, gastric and prostate cancers." (PMID 25245466, 2014). "An anti-CCR4 monoclonal antibody, mogamulizumab, has been approved for the treatment of mycosis fungoides and Sézary syndrome, and is under evaluation for use in other types of cancer." (PMID 41346591, 2025). "Targeting the receptor CCR4 represents a potential therapeutic strategy for cancer treatment." (PMID 38928238, 2024). "Considering that the cancer cells could have been affected directly by the pharmacological blockage of CCR4 in our experiments, which could be a valid explanation for the beneficial results." (PMID 37371612, 2023).
cancer (continued). "This suggests that the CCL2/CCR4 signaling pathway affects not only the chemoattraction and the migration machinery of cancer cells, but additionally modulates the neural ingrowth and innervation of cancer." (PMID 37607005, 2023). "Our experiment also verified that CCL22 was elevated in the HNSCC cell line CNE2, indicating that the CCL22/CCR4 axis might contribute to cancer progression in HNSCC." (PMID 36834729, 2023). "Therefore, targeting the CCL22-CCR4 axis by the anti-CCR4 antibody mogamulizumab or the CCR4 inhibitor AZD2098 is being tested as a promising strategy of cancer immunotherapy." (PMID 37207205, 2023). "Additionally, the mRNA levels of Treg chemokine receptors Ccr4, Ccr8, and Ccr10 as well as their ligands, Ccl1, Ccl17, and Ccl22 are significantly upregulated in the v-rasHa/ΔNp63α carcinomas compared to v-rasHa/Stuffer tumors or normal skin." (PMID 37638000, 2023). "The anti-CCR4 antibody, alone or in coadministration with other immune modulators, may be a potential treatment approach to cancer therapy." (PMID 36555280, 2022). "CCR4 expression has consistently been shown to mediate Treg migration in various cancer models." (PMID 33603130, 2022). "Furthermore, we identified that CCL2 and CCR4 was highly expressed in cancer cells of HNSCC, indicating that CCL2 secreted by cancer cells possibly stimulates itself by autocrine or paracrine function." (PMID 35177591, 2022). "Previous studies also showed that CAFs could produce the chemokine ligand CCL17 to act on CCR4 of cancer cells to improve cancer proliferation and migration." (PMID 35982908, 2022). "CCR4 influences the development of the inflammatory process, and subsequent researchers demonstrated the important role of this receptor in the processes of nociception, immunological diseases, and cancer." (PMID 36555280, 2022). "CCL17 and CCL22 promote stemness of cancer cells with CCR4 expression, drug resistance, stimulate the proliferation of cancer cells, and cause cancer cell migration and EMT, as shown on many types of cancers." (PMID 33182504, 2020). "Mogamulizumab is a mAB inhibitor of CCR4, and it is concurrently being investigated in both the phase I and II settings in advanced cancers including mRCC to assess safety and tolerability (NCT02281409) as well as clinical efficacy when in combination with nivolumab (NCT02946671)." (PMID 31484560, 2019). "Targeting CCR4 is an emerging strategy for immunotherapy for cancer." (PMID 30140381, 2018). "Prolonged depletion of CCR4+ Treg in the lymph nodes may prove to be beneficial in cancer treatment." (PMID 29873181, 2018). "Interestingly, an elevated expression of CCR4 in different types of human cancers has been related to a poor prognosis." (PMID 30140381, 2018). "CCR4 immunotoxin is therefore expected to avoid resistance mechanisms attributed to poor accessory cell function in immunocompromised and heavily pretreated cancer patients, as commonly occur with mAb therapy." (PMID 29873181, 2018). "One promising target for novel cancer immunotherapy is the CC chemokine receptor 4 (CCR4)." (PMID 28361224, 2017). "Finally, monoclonal antibodies against C-C chemokine receptor type 4 (CCR4) are being investigated as an approach to deplete or modulate Tregs in patients with cancer." (PMID 27330808, 2016). "This represents the first reported recurrent mutation in a member of the CCR4-NOT complex in cancer." (PMID 25544760, 2015). "In addition, the insights gained from the complex structure of mogamulizumab and its epitope peptide may offer critical information for designing a novel cancer vaccine that elicits an immune response against CCR4 for the treatment of CTCL." (PMID 40564964, 2025). "Previous research has shown that aberrantly high expression of CCL17 in various cancers, including leukemia, lung cancer, bladder cancer, breast cancer, gastric cancer, and liver cancer, serves as a primary driver for recruiting CCR4-expressing Tregs into the TME." (PMID 38914802, 2024).
cancer (continued). "As such, CCR4 targeting could enable novel cancer immunotherapies for solid tumors." (PMID 39114657, 2024). "Moreover, CCR4 is highly expressed in eTregs, and, thus, KW-0761 may selectively suppress eTregs via CCR4 and regulate cancer immunosuppression in patients treated with KW-0761." (PMID 37729184, 2023). "However, common CCR4-specifc ligands such as CCL5 show poor prognosis in these cancers." (PMID 37489388, 2023). "Indeed, the index for proximity between cancer and nerves was significantly increased after treatment with rCCL2 and decreased after CCR4 inhibition compared with control mice (mean index: rCLL2: 0.64, C021: 0.2, control: 0.43; mean scores: rCCL2: 28.2, C021: 8.8, control: 16.00)." (PMID 37607005, 2023). "Another study suggested that the presence of C-C chemokine receptor 4 (CCR4) on tumor-infiltrating Tregs, which enabled the migration of Tregs into cancer tissues by chemotaxis, might indicate men who may progress to castration-resistant prostate cancer (CRPC)." (PMID 35326519, 2022). "They suggest that the CCL17/CCR4 axis may drive Treg recruitment in a variety of canine cancers." (PMID 33692955, 2021). "Also, the observation that the anti-CCR4 antibody, Mogamulizumab, depletes CCR4 positive inhibitory T-regs in patients with cancer has paved the way for its evaluation in combination with other immune therapies for malignancies that are highly infiltrated with T-regs, including pMMR-MSI-L CRCs." (PMID 32090113, 2020). "Therefore, targeting CCR4 represents an emerging strategy for cancer therapy." (PMID 28415693, 2017). "Moreover, the chemokine receptor CCR4 might be involved in TNF-α-induced expression of MMP13 in CRC cells, suggesting the drugs targeting CCR4 may provide a clue for antagonizing TNF-α-regulated cancer cells metastasis." (PMID 27356745, 2016). "Collectively, CCR4 may play an important role in TNF-α-mediated cancer cells metastasis." (PMID 27356745, 2016). "Super-enhancers have been found in genes involved in T-cell activation (IL2RA/CD25, CD30, and FYN) and known cancer genes (TP73, CCR4, TIAM2, NFATC1, NFATC2, and PIK3R1) in ATL cells." (PMID 38791169, 2024). "CCL17 is a known STAT6 transcriptional target and chemoattractant that recruits various CCR4 + immune cells—such as CD8+ or CD4+ T-cells, and macrophages—in murine and canine cancer models, in addition to human tumors." (PMID 38285120, 2024). "Therefore, CCR4 may be a potential therapeutic target for those with early-stage cancer." (PMID 37259456, 2023). "Mechanistically, cancer-cell-derived TGF-α upregulated CCL2 secretion from sensory neurons, which induced hyperphosphorylation of the cytoskeletal protein paxillin via CCR4 on cancer cells." (PMID 37607005, 2023). "In comparison between cancer and adjacent control tissue, all the selected DEGs have been significantly changed in cancer CRC tissues, in exception to CCR4." (PMID 37869102, 2023). "Specifically, chemokines such as CXCL9, CXCL10, and CXCL11 and chemokine receptors such as CXCR5, CCR4, CCR8, and CCR1 were positively correlated with IGF2BP3 expression in various cancer types." (PMID 36761737, 2023). "Remarkably, though, treatment of both cancer cell lines SU.86.86 and T3M4 with the CCR4 antagonist (C021) decreased paxillin phosphorylation in a time-dependent manner." (PMID 37607005, 2023). "Several chemokine receptors, namely CCR4, CCR7, CCR9, and CXCR4, are substantially expressed in oncovirus-induced cancer cells." (PMID 35159113, 2022). "The results revealed that CD45 was positively correlated with the expression levels of genes characteristic of exhausted T cells across cancers, such as CXCL9, IL10, CD28, IDO1 and CCR4." (PMID 36061172, 2022). "Various other DT-based immunotoxins have also been studied, which are specifically targeted to cancers of interest, including cell-penetrating peptide BR2 and receptor of Treg cells, CCR4, DT386-BR2, and DT-anti-CCR4." (PMID 34960243, 2021).